EGFR (epidermal growth factor receptor)
Diseases named in the same sentence as EGFR in open-access papers (continued):
Sharing a sentence is not in itself a finding about the gene and the disease.
lung adenocarcinoma (continued). "EGFR-TKIs-challenged therapy for EGFR-mutant lung adenocarcinoma patients who acquired treatment resistance shows only moderate efficacy, and there were few pieces of research focused on the effect of Apatinib on EGFR-TKI resistance patients." (PMID 31570733, 2019). "Further studies are needed to explore the potential factors influencing response to EGFR-TKIs in lung adenocarcinoma with EGFR activating mutant." (PMID 31014278, 2019). "Epidermal growth factor receptor (EGFR) mutation, with exon 19 deletion, was seen more commonly in patients with adenocarcinoma of the lung and MPMs." (PMID 31275776, 2019). "Similar findings were noted in two additional patients with neuroendocrine transformation of EGFR mutant lung adenocarcinoma following treatment with EGFR inhibitors, both of whom showed reduced MHC-I staining in the transformed SCLC." (PMID 31564637, 2019). "The National Comprehensive Cancer Network (NCCN) guidelines now recommend routine testing for NTRK, ALK, ROS1, BRAF, and EGFR for all new cases of advanced lung adenocarcinoma for which we have therapies." (PMID 31134065, 2019). "With the increased use of epidermal growth factor receptor-tyrosine kinase inhibitors, the survival rate of lung adenocarcinoma patients has improved substantially." (PMID 31475114, 2019). "Here, we report that TGIF2 mediates the EGFR–RAS–ERK signaling pathway to enhance the stemness of lung adenocarcinoma (LUAD) cells and, therefore, promote the progression and metastasis of LUAD." (PMID 31871777, 2019). "The patients in Cohort 1 received epidermal growth factor receptor-tyrosine kinase inhibitor (EGFR-TKI) for recurrent lung adenocarcinoma." (PMID 31462002, 2019). "Few pieces of evidence have been published on the use of Apatinib Mesylate (AM) against EGFR-TKI resistance in lung adenocarcinoma (LA) patients." (PMID 31570733, 2019). "Patients and Methods: Metabolic parameters and clinicopathological data from 200 patients diagnosed with lung adenocarcinoma between July 2009 and November 2016, who underwent 18F-FDG PET/CT and EGFR mutation testing, were retrospectively evaluated." (PMID 31380265, 2019). "In recent years, molecular targeted therapy has been widely accepted for lung adenocarcinoma, and the epidermal growth factor receptor (EGFR) gene is a vital target of lung adenocarcinoma." (PMID 31174617, 2019). "In vitro, using plasmid transfection methods, PRDX4 plasmid DNAs were transfected into human lung adenocarcinoma cell lines, A549 (EGFR-wild) or PC-9 (EGFR mutant)." (PMID 31588184, 2019). "Herein, we report the case of a non-smoker male patient with multiple, large and diffuse brain metastases from an "epidermal growth factor receptor (EGFR) wild-type" lung adenocarcinoma who underwent an overly aggressive chemo/radiation therapy." (PMID 30979070, 2019). "Enhancing the chemosensitivity in the patients with epidermal growth factor receptor-tyrosine kinase inhibitor (EGFR-TKI) resistant lung adenocarcinoma (LUAD) is pivotal in achieving their successful therapeutic outcome." (PMID 30800222, 2019). "All patients had EGFR-mutant lung adenocarcinoma, and were administered EGFR-TKIs (91 gefitinib and 11 erlotinib) as the first-line treatment." (PMID 30609749, 2019). "Retrospective analysis of EGFR-mutant lung adenocarcinoma patients with brain metastases which developed at initial diagnosis or during EGFR-TKIs treatment period were performed." (PMID 31109441, 2019). "A recent study has confirmed the importance of the Golgi apparatus in overcoming the acquired resistance of lung adenocarcinoma to EGFR tyrosine kinase inhibitors." (PMID 30899432, 2019).
lung adenocarcinoma (continued). "Epidermal growth factor (EGFR) tyrosine kinase inhibitors (TKIs) are the standard care for patients with EGFR-mutant lung adenocarcinoma." (PMID 29321482, 2018). "In this context, also clinical studies have provided evidence that EGFR-mutant lung adenocarcinoma can transdifferentiate to squamous cell carcinoma in relapsed cancer patients." (PMID 30060526, 2018). "In our previous research, Lyn kinase was demonstrated to be an important factor up-regulating activity of EGFR and its downstream signaling pathway by phosphorylating tyrosine 845 of EGFR which suggests the therapeutic target for lung adenocarcinoma." (PMID 29892225, 2018). "In NSCLC, and especially in lung adenocarcinomas, signaling of kirsten human rat sarcoma protein (KRAS), a main downstream signaling molecule of EGFR pathway, is frequently influenced by its own somatic mutations." (PMID 30680072, 2018). "To date, there was no solid evidence that gefitinib or erlotinib had less efficacy than afatinib in first-line treatment of patients with EGFR-mutant lung adenocarcinoma and brain metastases." (PMID 30458751, 2018). "We investigate the effects of MMP-1 on migration and invasion abilities and the mechanism of induction of MMP-1 in EGFR-TKI–resistant lung adenocarcinoma." (PMID 29463039, 2018). "The most incident molecular alterations in lung adenocarcinoma, namely, KRAS mutations, EGFR mutations and ALK translocations, have been linked to MAPK activation." (PMID 29731995, 2018). "Mutations of the epidermal growth factor receptor (EGFR) gene and chromosomal rearrangement of the anaplastic lymphoma kinase (ALK) gene were among the first established molecular targets for therapy in lung adenocarcinoma." (PMID 29554880, 2018). "Because HER2 overexpression (IHC 2+ and 3+) is observed in 15–30% of lung adenocarcinoma and HER2 3+ and/or amplification is observed in 2–6% of lung adenocarcinoma, the pre-EGFR TKI treatment tumour samples were analysed for HER2 expression as well." (PMID 30061586, 2018). "EGFR over-expression and mutation have been demonstrated as an important factor for growth and progression of lung adenocarcinoma, but treatment efficacies of EGFR TKIs are weak and limited due to TKIs-related toxicities or high risk in part of patients." (PMID 29892225, 2018). "Patients with mutant EGFR-driven lung adenocarcinoma receiving EGFR tyrosine kinase inhibitor (TKI) therapy had better response rates and progression-free survival (PFS) when compared to those receiving traditional standard chemotherapy." (PMID 30444875, 2018). "This study demonstrated that enhanced YAP expression promoted the resistance of EGFR TKI in lung adenocarcinoma cells." (PMID 29321482, 2018). "In China, 80% of patients prefer receiving gefitinib over erlotinib for brain metastases following EGFR-mutant lung adenocarcinoma." (PMID 30458751, 2018). "In contrast to Asian lung adenocarcinoma patients, there is relatively less information about the first-line EGFR-TKI treatment response rates and progression-free survival in Caucasian cohorts." (PMID 29801465, 2018). "Lung adenocarcinoma is one of the diseases that frequently develop BM, and some disease-specific factors have been studied, such as, serum markers, epidermal growth factor receptor status (EGFR), tyrosine kinase inhibitor (TKI) therapy, and so on6." (PMID 29618796, 2018). "Yet overall survival (OS) and progression-free survival (PFS) remain controversial for Asian patients with exon 19 EGFR-mutant lung adenocarcinoma and brain metastases." (PMID 30458751, 2018).
lung adenocarcinoma (continued). "Out of the 651 screened patients, 62 with EGFR mutant lung adenocarcinoma were enrolled from 17 participating centers between March 2012 and January 2014." (PMID 29801465, 2018). "Mutations of TGFβR-II and SMAD4 are rare in NSCLC, whereas epidermal growth factor receptor (EGFR) and KRAS mutations are frequently found in lung adenocarcinomas." (PMID 30127261, 2018). "A good brain response in a patient with EGFR-mutant lung adenocarcinoma and multiple BMs who switched from erlotinib to afatinib due to hepatotoxicity, has been reported." (PMID 29881714, 2018). "In this case report, we present a male patient diagnosed with EGFR positive lung adenocarcinoma that partially responded to erlotinib, but eventually progressed." (PMID 29562902, 2018). "EGFR has been studied extensively in relation to lung adenocarcinoma to target the mutant EGFR using erlotinib." (PMID 29455652, 2018). "Analysis of these types of mutations, particularly in EGFR and KRAS, is typically part of the work-up of lung adenocarcinoma patients." (PMID 30115026, 2018). "Therefore, 142 EGFR mutations in exon 19 were chosen from approximately 601 cases of lung adenocarcinoma, and the finding that the scoring system about the distinction in EGFR mutation subtypes could be helpful and useful for selection of suitable clinical treatments." (PMID 30235778, 2018). "In order to inhibit the growth of EGFR-mutant lung adenocarcinomas, three generations of EGFR TKIs have been developed." (PMID 30060526, 2018). "Co-expression of NEDD4 with EGFR or PTEN was determined by immunohistochemical (IHC) staining in 63 lung adenocarcinoma tissue samples." (PMID 29455656, 2018). "Synthetic lethality results when mutant KRAS and EGFR proteins are co-expressed in human lung adenocarcinoma (LUAD) cells, revealing the biological basis for mutual exclusivity of KRAS and EGFR mutations." (PMID 30475204, 2018). "Inhibition of ANKRD1 led to induction of apoptosis by afatinib or osimertinib in adenocarcinoma cells, providing a critical therapeutic target for resistance to EGFR-TKIs in lung adenocarcinoma." (PMID 30291293, 2018). "MPV and LMR were independent predictors for shorter PFS in EGFR-mutant lung adenocarcinoma treated with EGFR-TKI." (PMID 30192878, 2018). "The testing cohort of 103 patients were all advanced EGFR-mutant lung adenocarcinoma patients, including 95 (92.2%) with acquired resistance to EGFR-TKIs and 8 (7.8%) with de novo T790M." (PMID 30444875, 2018). "The evidence in the previous literature regarding the optimal treatment strategy for the initial management of Asia patients with metastatic EGFR-mutant lung adenocarcinoma was questionable, although there are limited randomized trials directing this therapy." (PMID 30458751, 2018). "In the present study, we first demonstrated that ANKRD1 was commonly involved in anti-apoptosis and resistance to EGFR-TKIs in lung adenocarcinoma." (PMID 30291293, 2018). "Recently, a report showed that lower expression of NF1 was significantly correlated with primary and acquired resistance of lung adenocarcinomas to EGFR‐TKIs in patients." (PMID 29493886, 2018). "NF-1 deletion activates the MAPK pathway and was associated with the development of primary and acquired resistance of lung adenocarcinomas to EGFR TKIs in patients." (PMID 30445769, 2018). "EGFR, KRAS, HER2, BRAF, and PIK3CA mutations are these important genetic alterations in the targeted therapies of lung adenocarcinoma." (PMID 29518290, 2018). "We compared the migration ability of PC9/ER, which was EGFR-TKI–resistant lung adenocarcinoma cells with a high expression of MMP-1, and PC9/6m using a wound healing assay and migration assay for 24 h." (PMID 29463039, 2018). "Osimertinib had significantly greater efficacy than platinum therapy plus pemetrexed in lung adenocarcinoma with T790M-positive advanced NSCLC in whom disease had progressed during first-line EGFR-TKI therapy." (PMID 30060526, 2018).
lung adenocarcinoma (continued). "Epidermal growth factor receptor (EGFR) mutations are involved in the progression of NSCLC and the mutations of EGFR are most frequently found in lung adenocarcinoma cells." (PMID 30420490, 2018). "Both NEDD4 and EGFR are overexpressed in 41 lung adenocarcinoma samples out of total 63 samples, both overexpression rate in lung adenocarcinoma tumors are 65%." (PMID 29455656, 2018). "We evaluated the antitumor activities of afatinib and osimertinib in two EGFR-mutant lung adenocarcinoma cell lines, PC-9 and HCC827, by MTS assay." (PMID 30291293, 2018). "Recently, an interaction between the CRD region of human SP-D and N-glycans of EGFR has been reported which led to downregulated EGF signaling in human lung adenocarcinoma, A549 cell line cells." (PMID 29915574, 2018). "We investigated the impact of MPV and LMR on the prognosis of EGFR-mutant lung adenocarcinoma treated with EGFR-TKI." (PMID 30192878, 2018). "Epidermal growth factor receptor (EGFR) gene mutation is closely related to the EGFR-TKI target treatment and prognosis of lung adenocarcinoma patients." (PMID 29764589, 2018). "Immunohistochemical (IHC) staining of lung adenocarcinoma indicates that NEDD4 is co-expressed with EGFR." (PMID 29455656, 2018). "We analyzed data from 20 patients with advanced lung adenocarcinoma who acquired resistance to afatinib, including resistance during EGFR-TKI re-challenge." (PMID 30550608, 2018). "Levels of GAS5 were downregulated in the EGFR TKI resistant lung adenocarcinoma cell line A549 compared to sensitive cell lines." (PMID 29701689, 2018). "Detecting somatic mutations within epidermal growth factor receptor (EGFR) and anaplastic lymphoma kinase (ALK) driver gene status has become a diagnostic routine for lung adenocarcinoma." (PMID 29642919, 2018). "In their report, the authors described a connection between epidermal growth factor receptor (EGFR) tyrosine kinase inhibitor (TKI) resistance in lung adenocarcinoma cells with both YAP and PD-L1 expression." (PMID 29597279, 2018). "To conclude, this study provides insights into the development of a possible alternative therapy manipulating MMP-1 and the mTOR signaling pathway in EGFR-TKI–resistant lung adenocarcinoma." (PMID 29463039, 2018). "In lung adenocarcinoma, EGFR wild-type tumors have been characterized by higher density of neutrophils and macrophages." (PMID 30065206, 2018). "After the continuous expression of EGFR mutants, the bitransgenic mice developed invasive lung adenocarcinoma via the multistep continuum: the progression from AAH to AIS, followed by invasive adenocarcinoma with lepidic features." (PMID 29690599, 2018). "In fact, Sangodkar and coworkers have shown that in EGFR-mutant lung adenocarcinoma cells the KLF6 transcription factor is completely downmodulated via a transcriptional repressive effect mediated by the transcription factor FOXO1." (PMID 30060526, 2018). "We found that high MAP17 expression correlates with increased sensitivity to a variety of EGFR inhibitors in vitro and with increased sensitivity to erlotinib in lung adenocarcinoma PDX models with high EGFR activation." (PMID 30119639, 2018). "Driver oncogenes, such as ROS1 rearrangement, EGFR mutation, and ALK rearrangement, should be examined in putative lung adenocarcinoma similar to that in primary lung adenocarcinoma." (PMID 30443294, 2018). "Previously, it was reported that lung adenocarcinoma cells resistant to EGFR-TKI demonstrated a higher ability for invasion and migration than those sensitive to EGFR-TKI." (PMID 29463039, 2018). "EGFR targeted therapy brings hope for lung adenocarcinoma patients especially non-small cell lung cancer (NSCLC) patients." (PMID 29472856, 2018). "In a retrospective analysis in lung adenocarcinomas, c-MYC copy number gain was an independent poor-prognostic factor for disease-free and overall survival, with a possible association with EGFR mutation status." (PMID 29507657, 2018).
lung adenocarcinoma (continued). "Cell pellet, which includes cancer cells, was collected from pleural effusions in 27 patients with lung adenocarcinomas, of whom 18 were sensitive and nine were resistant to EGFR tyrosine kinase inhibitors." (PMID 29784046, 2018). "Here, we describe a 57-year-old man who was diagnosed with stage IIIB lung adenocarcinoma and EGFR/KRAS/ALK-negative tumors." (PMID 29361925, 2018). "We retrospectively analysed the prognostic impact of MPV in advanced or recurrent EGFR mutant lung adenocarcinoma treated with EGFR tyrosine kinase inhibitors (EGFR-TKIs)." (PMID 30192878, 2018). "Lung adenocarcinoma patients with WSE showed a distinctive mutated profile for the SMARCB1, ATM, EGFR exon 7, RET and KDR genes." (PMID 30093964, 2018). "The present study demonstrated that high MPV, low LMR and pleural effusion were independent predictors for shorter PFS in EGFR-mutant lung adenocarcinoma treated with EGFR-TKI." (PMID 30192878, 2018). "Apart from HER2 over-expression and amplification, HER2 gene mutation is a distinct entity in lung carcinogenesis with an incidence of 4.8% among EGFR wild-type lung adenocarcinoma resection samples." (PMID 29587667, 2018). "Epidermal growth factor (EGF) and its receptor (EGFR), which is most closely related to lung adenocarcinoma, were discovered by Stanley Cohen of Vanderbilt university in 1986." (PMID 30383772, 2018). "The purpose of this study was to compare clinical outcomes of Erlotinib versus Gefitinib in the treatment of Asian patients with exon 19 EGFR-mutant lung adenocarcinoma and newly diagnosed brain metastases." (PMID 30458751, 2018). "EGFR-mutant lung adenocarcinomas (LUAD) display diverse clinical trajectories and are characterized by rapid but short-lived responses to EGFR tyrosine kinase inhibitors (TKIs)." (PMID 29335443, 2018). "This has increasingly become a consensus that the supreme benefit of EGFR-TKI therapy occurred in patients with EGFR-mutant lung adenocarcinoma and brain metastases." (PMID 30458751, 2018). "The development of acquired EGFR‐TKI therapeutic resistance is still a serious clinical problem in the management of lung adenocarcinoma." (PMID 29573196, 2018). "EGFR mutant lung adenocarcinoma (LUAD) exhibit diverse clinical outcomes in response to targeted therapies." (PMID 29335443, 2018). "A 62-year-old man was referred to our university hospital for treatment of advanced adenocarcinoma of the lung after disease progression on two lines of EGFR TKI and one line of chemotherapy." (PMID 29872644, 2018). "EGFR is genetically activated in a substantial population of lung adenocarcinomas, and EGFR inhibitors were proven to be highly effective in treating this genetically defined subpopulation of cancer." (PMID 30443290, 2018). "The present study is the first to examine the significance of MMP-1 in EGFR-TKI–resistant lung adenocarcinoma." (PMID 29463039, 2018). "The use of any first- or second-generation EGFR-TKIs alone for the treatment of brain metastases in patients with EGFR mutant-positive lung adenocarcinoma showed a favorable cerebral response rate of > 50%." (PMID 29805772, 2018). "Of 26 EGFR-mutant lung adenocarcinoma patients with acquired resistance to gefitinib or erlotinib, 3 (12%) were detected with ErbB2 amplification by FISH analysis." (PMID 29455669, 2018). "Consecutive Asian patients with exon 19 EGFR-mutant lung adenocarcinoma and newly diagnosed brain metastases were identified and initially received peroral administration of 150 mg/d erlotinib or 250 mg/d gefitinib during 2009–2015." (PMID 30458751, 2018). "A 57-year-old Hispanic male patient initially diagnosed with an EGFR 19 deletion positive lung adenocarcinoma and clinically responded to initial erlotinib treatment." (PMID 29562902, 2018). "EGFR tyrosine kinase inhibitors (TKIs) have been used in patients with EGFR-mutant as an effective targeted therapy in lung adenocarcinoma, but drug resistance and tumor recurrence inevitably occurs." (PMID 29321482, 2018).